AIRE (autoimmune regulator)
Diseases named in the same sentence as AIRE in open-access papers (continued):
Sharing a sentence is not in itself a finding about the gene and the disease.
autoimmune polyendocrine syndrome type 1 (continued). "Expression of some TSAs in mTECs is controlled by the autoimmune regulator (AIRE) protein, of which dysfunctional mutations are the causative factor of autoimmune polyendocrinopathy-candidiasis-ectodermal dystrophy (APECED)." (PMID 23986760, 2013). "Autoimmune polyendocrinopathy-candidiasis-ectodermal dystrophy (APECED) is an autosomal recessive condition due to mutation of the Autoimmune regulator (AIRE) gene." (PMID 23630524, 2013). "Anti-IFN-ω autoantibodies have been reported in several other autoimmune diseases, including in late-onset myasthenia gravis, and are associated with mutations in the autoimmune regulator (AIRE) gene in autoimmune polyendocrine syndrome type 1." (PMID 22363785, 2012). "Autoimmune polyendocrinopathy-candidiasis-ectodermal dystrophy (APECED) is a rare autosomal recessive disorder caused by mutations in the autoimmune regulator gene (AIRE)." (PMID 21197407, 2010). "Mutations in the AIRE gene cause a rare disease named autoimmune polyendocrinopathy-candidiasis-ectodermal dystrophy (APECED)." (PMID 17997173, 2008). "Autoimmune polyendocrinopathy candidiasis ectodermal dystrophy is a rarerecessive autoimmune disorder caused by a defect in a single gene called AIRE(autoimmune regulator)." (PMID 16295527, 2005). "Mutations in AIRE lead to a rare monogenic disorder called autoimmune polyendocrinopathy-candidiasis-ectodermal dystrophy (APECED), and mono-allelic mutations in the PHD1 finger of AIRE have been found to associate with a broader range of autoimmune phenotypes." (PMID 40568090, 2025). "Autoimmune polyendocrine syndrome type 1 (APS-I) is a rare monogenic autoimmune condition caused by mutations in the Autoimmune Regulator (AIRE) gene, although other genetic determinants may influence the phenotype and severity." (PMID 40759705, 2025). "We report a loss-of-function, germline, homozygous variant in the AIRE gene associated with APECED syndrome and a gain-of-function variant in mitogen-activated protein kinase kinase kinase 3 (MAP3K3), previously identified in patients with cerebral cavernous malformations (CCMs)." (PMID 41190326, 2025). "Autoimmune polyglandular syndrome type 1 is characterized by a classic triad of hypoparathyroidism, adrenal insufficiency, and candidiasis as a result of homozygous loss-of-function mutations in the AIRE gene." (PMID 38255237, 2024). "Dysregulation of the autoimmune regulator (AIRE) gene by miR-220b may be a causal factor for autoimmune polyendocrinopathy-candidiasis-ectodermal dystrophy (APECED) or its related diseases." (PMID 38339220, 2024). "APS Type 1 originates from loss-of-function mutations in the autoimmune regulator (AIRE) gene." (PMID 39456777, 2024). "Informative syndromes caused by errors in essential immune genes like AIRE (autoimmune polyendocrine syndrome type 1, APS-1) and NFKB2 (DAVID syndrome) causing autoimmune disease in the adrenals either as a primary or secondary, further throw light on parts of the pathogenesis of autoimmune PAI." (PMID 38027140, 2023). "The AIRE gene causing APECED syndrome was first identified in 1997." (PMID 37144156, 2023). "The risk of type 1 diabetes (T1D) is higher in patients with IPEX (FOXP3, forkhead box P3), WHIM syndrome, autoimmune polyglandular syndrome type 1 (APS type 1 due to AIRE mutation), CTLA4 mutation, deficiency of LRBA, milder forms of ADA deficiency, and STAT1 GOF." (PMID 37102642, 2023). "Loss of functioning AIRE protein leads to defective removal of self-reactive T-lymphocytes and autosomal recessive homozygous or compound heterozygous AIRE mutations give rise to APECED syndrome characterized by multi-organ autoimmunity." (PMID 35241125, 2022).
autoimmune polyendocrine syndrome type 1 (continued). "Autoimmune polyendocrinopathy candidiasis ectodermal dystrophy (APECED) is an autosomal recessive disease caused by mutations in the autoimmune regulator (AIRE) gene, characterized by the clinical triad of chronic mucocutaneous candidiasis (CMC), hypoparathyroidism, and adrenal insufficiency." (PMID 30510552, 2018). "Indeed, loss-of-function mutations in the AIRE gene lead to the autoimmune polyendocrinopathy candidiasis ectodermal dystrophy (APECED) syndrome also known as APS for autoimmune polyglandular syndrome." (PMID 28167946, 2017). "Autoimmune polyendocrinopathy-candidiasis-ectodermal dystrophy (APECED) is a rare primary immunodeficiency disorder typically caused by biallelic autoimmune regulator (AIRE) mutations that manifests with chronic mucocutaneous candidiasis (CMC) and autoimmunity." (PMID 28769929, 2017). "Autoimmune polyendocrine syndrome type 1, also known as autoimmune polyendocrinopathy-candidiasis-ectodermal-dystrophy, is a rare autosomal recessive disease due to pathogenic variants in the AIRE gene." (PMID 25361846, 2014). "Autoimmune polyendocrinopathy candidiasis ectodermal dystrophy (APECED) is a rare autosomal recessive disorder caused by mutations of the autoimmune regulator (AIRE) gene, whose loss of function leads to the escape of self-reactive T cells from the thymus and autoimmunity." (PMID 23781320, 2013). "Pathogenic variants in the autoimmune regulator gene (AIRE) cause Autoimmune polyendocrine syndrome type 1 (APS-1)." (PMID 42262224, 2026). "This is exemplified by the monogenic disorder autoimmune polyendocrine syndrome type 1 (APS-1), caused by mutations in the AIRE gene." (PMID 40852720, 2025). "Mutations in the AIRE gene give rise to autoimmune polyendocrine syndrome type 1 (APS1), which is an autoimmune disease that can affect multiple organs in the body." (PMID 39168282, 2024). "Autoimmune polyendocrine syndrome type 1 (APS-1) arises from mutations in the Autoimmune regulator (AIRE) gene, situated on 21q22.3." (PMID 39095891, 2024). "Autoimmune polyendocrine syndrome type 1 (APS-1) is a rare monogenic disease caused by mutations in the autoimmune regulator gene." (PMID 38829425, 2024). "Furthermore, APECED syndrome with biallelic mutations in the AIRE gene and HIES with dominant-negative mutations in the STAT3 gene are also characterized by increased susceptibility to fungal infections, which may manifest as CMC." (PMID 38327523, 2024). "Autoimmune polyendocrine syndrome type 1 (APS-1) is caused by mutations in the autoimmune regulator (AIRE) gene." (PMID 37909333, 2023). "Autoimmune polyendocrine syndrome type 1 (APS-1) is an autosomal recessive disease characterized by severe and childhood onset organ-specific autoimmunity caused by mutations in the autoimmune regulator (AIRE) gene." (PMID 37235056, 2023). "The pathogenesis of these auto-Abs is largely unknown, but they can be detected in children or adults with IEI underlying broader autoimmunity, such as germline loss-of-function biallelic (or monoallelic) mutations of AIRE underlying autoimmune polyendocrine syndrome type 1 (APS-1)." (PMID 35319722, 2022). "Autoimmune polyendocrine syndrome type 1 (APS-1) is a rare, childhood onset disease caused by mutations in the autoimmune regulator (AIRE) gene." (PMID 28919897, 2017). "Interestingly, mucocutaneous candidiasis has been seen in association with anti-IL-17 and anti-IL-22 autoantibodies in autoimmune polyendocrinopathy candidiasis ectodermal dystrophy (APECED) syndrome, caused by a Mendelian deficiency of the autoimmune regulator (AIRE) gene." (PMID 25426445, 2014).
autoimmune polyendocrine syndrome type 1 (continued). "The autoimmune polyendocrine syndrome type 1 (APS-1) is a monogenic disease due to pathogenic variants occurring in the autoimmune regulator (AIRE) gene." (PMID 23125865, 2012). "For example, T1DM occurs in up to 18% of patients with autoimmune polyendocrinopathy-candidiasis-ectodermal dystrophy (APECED), caused by functional defects in AIRE, a gene responsible for assessing the self-avidity of developing T-cells in the thymus." (PMID 40704637, 2025). "Up to 60% of cases diagnosed with APS-1(autoimmune polyendocrinopathy-candidiasis-ectodermal dystrophy - APECED),characterized by mutations in the autoimmune regulator(AIRE) gene, will develop POI." (PMID 41337668, 2025). "Autoimmune-polyendocrinopathy-candidiasis-ectodermal dystrophy (APECED; OMIM #240300) is a disorder arising from mutations in the autoimmune regulator (AIRE) gene (21q22.3)." (PMID 38578980, 2025). "Autoimmune polyendocrine syndrome type 1 (ORPHA: 3453), caused by various mutations in the autoimmune regulator (AIRE) gene on chromosome 21, is characterized by the presence of candidiasis, hypoparathyroidism, and Addison’s disease." (PMID 40495344, 2025). "Pathogenic variants in the Autoimmune Regulator (AIRE) gene cause Autoimmune Polyendocrine Syndrome Type 1 (APS-1), a rare primary immunodeficiency disease with symptoms including hypoparathyroidism, adrenal insufficiency, and chronic mucocutaneous candidiasis." (PMID 41332640, 2025). "An exemplary case was demonstrated in patients with autoimmune polyendocrine syndrome type 1 (APS1), which is caused by autosomal recessive mutations in the AIRE gene." (PMID 38462559, 2024). "The case of a seven-year-old male patient with hypocalcemia reported in this article serves as an illustration, wherein targeted next-generation sequencing revealed a homozygous p.R257X mutation in the AIRE gene, indicative of autoimmune polyendocrine syndrome type 1 (APS-1)." (PMID 38673639, 2024). "Autoimmune polyendocrine syndrome type 1 (APS-1), also called autoimmune polyendocrinopathy-candidiasis-ectodermal dystrophy (APECED), is a rare monogenic disease caused by mutations in the autoimmune regulator (AIRE) gene." (PMID 38829425, 2024). "Autoimmune-polyendocrinopathy-candidiasis-ectodermal dystrophy (APECED, OMIM240300) syndrome is a rare monogenic disease due to biallelic mutations in autoimmune regulator (AIRE) gene." (PMID 37457714, 2023). "Chronic mucocutaneous candidiasis (CMC) is pathognomonic of autoimmune polyendocrine syndrome type 1 (APS-1), a monogenic deficiency in an autoimmune regulator gene." (PMID 37998910, 2023). "Autoantibodies against type 1 interferons (IFN-I) are highly specific for type 1 autoimmune polyglandular syndrome (APS-1), a monogenic disease caused by a mutation in the AIRE gene." (PMID 36556169, 2022). "Patients with autoimmune polyendocrine syndrome type 1 (APS-1), who have a defect central T cell tolerance and are consequently prone to develop autoimmune disease due to biallelic germline AIRE mutations, have been shown to produce high titres of IFN-I auto-antibodies." (PMID 35986347, 2022). "Some mutations in the AIRE gene are related to autoimmune polyendocrinopathy-candidiasis ectodermal dystrophy (APECED), also known as autoimmune polyglandular syndrome type 1 (APS-1) (OMIM entry # 240300)." (PMID 36148232, 2022). "Another gene involved in central tolerance is AIRE (Autoimmune Regulator Gene); its loss of function can lead to the APS1 (autoimmune polyendocrine syndromes type 1)." (PMID 36578493, 2022). "Autoimmune-Polyendocrinopathy-Candidiasis-Ectodermal-Dystrophy (APECED), also known as Autoimmune Polyendocrine Syndrome type 1 (APS-1), is a rare and severe multiorgan autoimmune disease caused by mutations in Autoimmune Regulator (AIRE)." (PMID 35432216, 2022).
autoimmune polyendocrine syndrome type 1 (continued). "This potentially lethal disease can occur in isolation or as a component of autoimmune polyendocrine syndrome types 1 (APS-1) or 2 (APS-2), the former being a monogenic disorder caused by mutations in the AIRE gene." (PMID 34721410, 2021). "Autoimmune polyendocrinopathy-candidiasis-ectodermal dystrophy (APECED), also known as autoimmune polyglandular syndrome type-1 (APS-1), is a rare monogenic autoimmune disease caused by loss-of-function mutations in the autoimmune regulator (AIRE) gene." (PMID 34790633, 2021). "APECED (autoimmune polyendocrinopathy-candidiasis-ectodermal dystrophy, OMIM #240300) is a rare autoimmune disease caused by autosomal recessive mutations in the gene encoding the Autoimmune Regulator (AIRE)." (PMID 34367134, 2021). "Autoimmune polyendocrinopathy-candidiasis-ectodermal dystrophy (APECED), also called autoimmune polyendocrine syndrome type I (APS-I), is a rare disorder arising from mutations in the autoimmune regulator (AIRE) gene." (PMID 34917035, 2021). "In autoimmune polyendocrinopathy-candidiasis-ectodermal dystrophy (APECED) defects in the autoimmune regulator gene lead to impaired immunotolerance." (PMID 34917035, 2021). "Autosomal recessive CMC results from a rare condition, autoimmune polyendocrinopathy candidiasis ectodermal dystrophy (APECED), which in turn results from mutations in the autoimmune regulator (AIRE) gene." (PMID 32352976, 2020). "Autoimmune-polyendocrinopathy-candidiasis-ectodermal dystrophy (APECED), also known as autoimmune polyglandular syndrome type-1 (APS-1), is a rare disorder resulting from biallelic mutations in the autoimmune regulator (AIRE) gene." (PMID 33584685, 2020). "Although the Aire gene mutations lead to autoimmune polyendocrinopathy candidiasis ectodermal dystrophy (APECED), the mechanism of AIRE downregulation and T-bet upregulation in thymic ABCs remains uncharacterized." (PMID 31795353, 2019). "Two had the same homozygous mutation in the autoimmune regulator (AIRE) gene, which is associated with type 1 autoimmune polyglandular syndrome." (PMID 27485500, 2016). "In AAD such a monogenic form exists, as the autoimmune polyendocrinopathy syndrome type 1 (APS1), caused by loss of function mutations to both alleles of the AIRE gene." (PMID 24614117, 2014). "Here is a real life example of variation in the AIRE gene leading to the autoimmune polyendocrine syndrome type 1 (APS-1) also called for APECED disease (autoimmune polyendocytopathy-candidiasis-ectodermal dystrophy), an autoimmune polyendocrine syndrome." (PMID 24533660, 2014). "The development of APS1, formerly autoimmune polyendocrinopathy-candidiasis-ectodermal dystrophy (APECED), is attributed to the loss of function mutation and dysregulation of the AIRE gene." (PMID 24895619, 2014). "Studies on autoimmune polyendocrinopathy candidiasis ectodermal dystrophy (APECED) and its mouse model – both caused by mutant AIRE – have greatly advanced the understanding of thymic processes that generate a self-tolerant T-cell repertoire." (PMID 24592265, 2014). "Autoimmune regulator (AIRE) gene mutation is responsible for the development of autoimmune-polyendocrinopathy-candidiasis ectodermal dystrophy (APECED), also known as autoimmune polyglandular syndrome type 1 (APS1), an organ-specific autoimmune disease." (PMID 24917867, 2014). "Loss-of-function mutations in the Autoimmune Regulator (AIRE) gene cause a rare inherited form of autoimmune disease, autoimmune polyendocrinopathy-candidiasis-ectodermal dystrophy, also known as autoimmune polyglandular syndrome type 1." (PMID 24109480, 2013). "Autoimmune polyendocrinopathy-candidiasis-ectodermal dystrophy (APECED) is a rare autosomal recessive disease, caused by mutations of a single gene named Autoimmune regulator gene (AIRE) which results in a failure of T-cell tolerance." (PMID 24167503, 2013).
autoimmune polyendocrine syndrome type 1 (continued). "Autoimmune Polyglandular Syndrome Type 1 (APS-1), also called Autoimmune polyendocrinopathy-candidiasis-ectodermal dystrophy (APECED), is a rare autosomal recessive disease caused by mutations of the autoimmune regulator gene (AIRE)." (PMID 24167503, 2013). "Autoimmune polyendocrinopathy candidiasis ectodermal dystrophy (APECED) is a rare autosomal recessive disease, caused by mutations of a single gene named autoimmune regulator gene (AIRE) which results in a failure of T cell tolerance within the thymus." (PMID 23133448, 2012). "AIRE (autoimmune regulator) is a defective gene in APECED (autoimmune-polyendocrinopathy-candidiasis-ectodermal dystrophy, OMIM #240300), the genetic autoimmune disease, which manifests as autoimmunity to multiple endocrine glands." (PMID 17997173, 2008). "It is the most common aetiology of primary adrenal insufficiency in developed countries and the condition can occur in isolation or as a component of autoimmune polyendocrine syndrome types 1 (APS-1) or 2 (APS-2), the former being a monogenic disorder caused by mutations in the AIRE gene." (PMID 40607215, 2025). "Mutations in the AIRE gene have been associated with a rare inherited autoimmune disorder denominated autoimmune polyendocrine syndrome type 1 (APS‐1), also known as APECED (autoimmune polyendocrinopathy candidiasis ectodermal dystrophy)." (PMID 41429646, 2025). "Autoimmune polyendocrinopathy-candidiasis-ectodermal dystrophy (APECED), known also as autoimmune polyendocrine syndrome type 1 (APS1), arises from damaging genetic germline mutations in the autoimmune regulator (AIRE) gene, leading to multiple autoimmune diseases in affected individuals." (PMID 39440452, 2024). "APS-1 is a rare autosomal recessive disease, also known as autoimmune-polyendocrinopathy-candidiasis-ectodermal dystrophy (APECED), caused by variants in the autoimmune regulator gene (AIRE), which is expressed in thymic medullary epithelial cells and dendritic cells." (PMID 36763264, 2023). "It was established that in patients with APECED syndrome or AIRE-deficient mice, the negative selection of self-reactive B-cells was impaired on the periphery, which is normally provided by an inhibiting influence of Treg lymphocytes." (PMID 35053310, 2022). "Inherited AIRE mutations affect the thymic negative selection, resulting in a multi-organ disease autoimmune polyendocrinopathy syndrome type 1 (APS1)." (PMID 34440825, 2021). "Autoimmune polyendocrine syndrome type 1 (APS1) is a hereditary disease caused by mutations in the AIRE gene with both endocrine and non-endocrine organ involvement." (PMID 34217342, 2021). "Autoimmune polyendocrinopathy-candidiasis-ectodermal dystrophy (APECED; OMIM, 240300), also termed autoimmune polyendocrine syndrome type 1, is a rare monogenic autosomal recessive disease caused by mutations in the autoimmune regulator (AIRE) gene." (PMID 34122451, 2021). "Autoimmune Polyglandular Syndrome type 1 (APS-1) is a rare recessive inherited disease, caused by AutoImmune Regulator (AIRE) gene mutations and characterized by three major manifestations: chronic mucocutaneous candidiasis (CMC), chronic hypoparathyroidism (CH) and Addison’s disease (AD)." (PMID 34003463, 2021). "Identifying AIRE mutations as the cause of the APECED syndrome has deepened the understanding of negative selection." (PMID 33537838, 2021). "Autoimmune polyendocrinopathy-candidiasis-ectodermal dystrophy (APECED; OMIM 240300) or autoimmune polyglandular syndrome type 1 (APS1) is an autosomal-recessive disorder caused by mutations in the autoimmune regulator (AIRE) gene." (PMID 32210917, 2020). "Studies of a rare monogenic disorder – autoimmune polyendocrine syndrome type 1 (APS1) or autoimmune polyendocrinopathy-candidiasis-ectodermal dystrophy (APECED) and the mutated gene underlying the disease, Autoimmune regulator (AIRE) – have shed light on how reaction against self is avoided." (PMID 31244471, 2019).